TERT (telomerase reverse transcriptase)
Diseases named in the same sentence as TERT in open-access papers (continued):
Sharing a sentence is not in itself a finding about the gene and the disease.
glioma (continued). "In gliomas, the prevalence of mutations on the TERT promoter is remarkably high in primary GBMs (approximately 80%), and recent evidence suggested the presence of TERT promoter mutations as an unfavorable prognostic factor in GBM." (PMID 33053763, 2020). "In this study, we conducted a comprehensive meta-analysis to further understand whether TERT promoter mutation has any interaction with MGMT promoter methylation on overall survival (OS) of glioma patients." (PMID 32957941, 2020). "TERT promoter mutations which result in increased TERT expression were first identified in melanoma and were subsequently reported in other cancers like bladder cancer, glioma, thyroid cancer and HCC." (PMID 32722302, 2020). "Combined with its adverse effect on survival among IDH-wild glioma cases, the bivalent prognostic impact of TERT promoter mutation may help further refine the molecular diagnosis and prognostication of diffuse gliomas." (PMID 33228806, 2020). "TERT promoter mutations are commonly associated with 1p/19q codeletion in IDH-mutated gliomas." (PMID 33228806, 2020). "TERT promoter mutations were detected in 20 out of 41 (48.8%) gliomas." (PMID 32599896, 2020). "In addition, TERT promoter mutation seems to be a useful biomarker in clinically evaluating sensitivity to TMZ for treatment of glioma patients who carry MGMT methylated status." (PMID 32957941, 2020). "TERT promoter mutations are present in a high percentage of gliomas (80–90%)." (PMID 33198352, 2020). "In MGMT-meth gliomas, TERT promoter mutation was correlated with a favorable survival outcome." (PMID 32957941, 2020). "TERT promoter mutation was detected in 34 of 56 (60.7%) gliomas." (PMID 31111685, 2020). "TERT = TERT copy number variant gain in NF1-Glioma and TERT promotor expression in LGm6 group." (PMID 31906320, 2020). "Indeed, two genetic variants located near the telomerase genes TERC and TERT are associated both with increased risk of high-grade glioma and with longer telomere length." (PMID 33198352, 2020). "Interestingly in our results 1p/19q codeleted gliomas showed a higher percentage of TERT promoter mutations – 94%." (PMID 31623593, 2019). "Hence, in this study we sought to elucidate the role of concomitant BRAFV600E and TERT promoter mutations in the malignant phenotype of glioma, to dissect the involvement of different ETS-factors and investigate potential therapeutic implications." (PMID 31391125, 2019). "Interestingly, we found that HOTAIR and EZH2 were highly co-expressed in TERT mutations only subtype of glioma and triple-negative subtype of breast cancer." (PMID 31367244, 2019). "Additionally, we demonstrated that HOTAIR and EZH2 are highly co-expressed in TERT Mutation Only subtype of glioma and triple-negative subtype of breast cancer." (PMID 31367244, 2019). "A case-control study recruited 855 high-grade glioma patients from four different geographic regions of the US and belonging to five inherited glioma risk variants: 5p15.3 (TERT), 8q24.21 (CCDC26/MLZE), 9p21.3 (CDKN2B), 11q23.3 (PHLDB1/DDX6) and 20q13.3 (RTEL1)." (PMID 30909395, 2019). "In a previous study we demonstrated that TERT promoter mutations could identify among lower-grade gliomas a group of IDH-mutated-1p/19q-intact tumors with better survival and a subset of IDH wild-type tumors with worse prognosis." (PMID 31444316, 2019).
glioma (continued). "Mutations of ATRX and of TERT are not sufficient as possible indications for ALT- and TEL-TMM because loss of ATRX coexist with TEL-TMM in some cell lines and melanomas, which can show ATRX and TERT mutations in parallel, while they are mutually exclusive in in glioma." (PMID 31750255, 2019). "Consequently, we systematically investigated the cellular factors contributing to the interplay of BRAFV600E and TERT promoter mutations in glioma." (PMID 31391125, 2019). "Gliomas with a WT TERT promoter frequently harbor mutations of ATRX to activate ALT." (PMID 30625996, 2019). "In addition, ARID1A and PIK3CA mutations also tend to be mutually exclusive with TERT promoter mutations in ovarian clear cell carcinoma or glioma." (PMID 30709063, 2019). "Early 2017 the platform has been revised and expanded, to allow detection of mutations in de TERT promoter, in genes important for pediatric brain tumors and other adult non-glioma brain tumors and more CNA’s (including 9p, 17) that are relevant for pediatric, adolescents and young adults." (PMID 30470264, 2018). "Nevertheless, a potential role of TERT promoter mutations to promote proliferation in the initial growth phase and as a glioma initiation event is speculative and will be discussed later in this review." (PMID 29616301, 2018). "An intriguing hypothesis to test would, therefore, be to examine the impact of allele-specific effects of rs10069690 on telomere length in the context of gliomas carrying the TERT promoter mutation." (PMID 29460007, 2018). "The presence of TERT promoter mutations is well-correlated with three distinctive glioma groups, suggesting that TERT could be deeply involved in the biology of diffuse gliomas." (PMID 29693015, 2018). "Although the timing of TERT promoter mutations is still under debate, several lines of evidence suggest that TERT promoter mutations arise early in gliomagenesis and perhaps even occur prior to the glioma initiation event." (PMID 29616301, 2018). "Comparisons of groups based on the statuses of IDH, 1p19q, and TERT revealed that TERT mutation bestows better outcomes in gliomas with TERT mutant/IDH mutation/1p19q co-deletion, but poorer survival in GBM with TERT mutant/IDH mutation without 1p19q co-deletion." (PMID 29899215, 2018). "Meanwhile, TERT mutation only glioma has deep-seated location than triple-positive cases." (PMID 28915860, 2017). "Besides, TERT promoter mutations were associated with poor clinical outcomes in glioblastoma patients and in lower-grade gliomas." (PMID 29262650, 2017). "Apart from lung cancer, glioma, and bladder cancer, our meta-analysis also investigated the association between the TERT rs2736100 polymorphism and risk of colorectal cancer (4 studies), MPN, gastric cancer, AML, breast cancer, melanoma, and thyroid cancer as well as “other cancers”." (PMID 28418878, 2017). "The presence of TERT mutations is also important for glioma prognosis, since gliomas (in particular LGGs) with concomitant IDH and TERT mutations are associated with better prognosis, while patients with IDH-wildtype and TERT mutated GBMs have poorer prognoses." (PMID 28915660, 2017). "We analyzed the correlation between TERT rs2853676 genetic polymorphisms and glioma prognosis, to identify possible points of intervention that may lead to improved patient survival." (PMID 27655710, 2016). "However, we found highly frequent ATRX inactivation (∼92.9%) in TERT wild-type gliomas, and there was a significantly inverse relationship between TERT promoter mutations and ATRX inactivation." (PMID 26556853, 2016). "In summary, we investigated TERT promoter mutations and alteration of telomere length in a large cohort of primary gliomas in Northwest China, and demonstrated that these mutations and long telomere length were closely associated with aggressive tumor behaviors and poor patient survival." (PMID 26556853, 2016).
glioma (continued). "Interestingly, TERT rs2736100 has been found to be associated with risk of lung cancer, glioma, testicular cancer,colorectal cancer, acute myeloid leukemia, pancreatic cancer and bladder cancer." (PMID 26716642, 2016). "Moreover, to our knowledge, the present study is the first to show that TERT promoter mutations and long telomere length affect radiotherapy outcome in glioma patients." (PMID 26556853, 2016). "In conclusion, our study indicates that TERT rs2853676 polymorphisms correlate with glioma survival and recurrence rates, suggesting that they may serve as diagnostic markers to improve glioma treatment." (PMID 27655710, 2016). "Recurrent mutations in the promoter region of TERT gene, namely the c.-146:C > T and the c.-124:C > T mutations, were recently reported in several tumors, including melanomas, bladder, hepatocarcinoma, thyroid carcinomas, and gliomas." (PMID 27172220, 2016). "We previously demonstrated that TERT promoter mutations may be promising biomarkers in glioma survival prognostication when combined with IDH mutations." (PMID 26314843, 2015). "Expression data and an association with shorter telomeres already strongly indicate the role of the TERT promoter mutations not only in glioma, but many other cancer types, and future functional studies will aid placing the TERT promoter mutations into the right context." (PMID 25797251, 2015). "Overall TERT promoter mutations were present in 199 of 303 (66%) gliomas." (PMID 25797251, 2015). "In addition, ATRX mutation and TERT promoter mutation were identified as biomarker in lower-grade gliomas." (PMID 26468983, 2015). "Interestingly, the TERT promoter mutation always occurred in the setting of patients with IDH1/2 mutation and this mutation highly correlated with upregulated TERT mRNA expression and tumor grade in adult gliomas." (PMID 26468983, 2015). "TERT promoter mutations frequently occur across all types of gliomas, suggesting regulation of telomere elongation by telomerase may play an important role in the pathogenesis of gliomas." (PMID 26314843, 2015). "Besides reporting a high frequency of TERT promoter mutations in different glioma types, we describe the correlations with IDH mutations and deletions at 1p, 19q and CDKN2A/B loci that have prognostic implications." (PMID 25797251, 2015). "Up regulation of TERT expression is abundantly reported in somatic cells and two hot spot mutations in the TERT promoter, −228C > T and −250C > T, were recently reported in several different solid tumors e.g melanoma and gliomas." (PMID 26298771, 2015). "In glioma, genome-wide association studies have identified common genetic variations in 7 genes that increase glioma risk (TERT, EGFR, CCDC26, CDKN2A, CDKN2B, PHLDB1 and RTEL1) but BRCA1 is not among them and there is no known association between BRCA1 gene and glioblastoma multiforme (GBM)." (PMID 25880076, 2015). "A multivariate model on progression-free survival in low grade gliomas showed that TERT promoter mutations are associated with poor survival (HR = 10.2; 95% HR CI 1.9 – 55.9; P = 0.007) and 1p/19q codeletions have a protective effect (HR = 0.03; 95% HR CI 0.004 – 0.173; P = 0.0001)." (PMID 25797251, 2015). "Thus, the effect of TERT promoter mutations on TERT mRNA expression in gliomas was examined by qRT-PCR." (PMID 24937153, 2014). "As grade is a well-known prognostic factor in glioma patients, we first investigated whether distinct tumor subgroups could be distinguished using only TERT promoter and IDH1/2 mutation status within each grade." (PMID 24722048, 2014). "The impact of TERT promoter mutations on patient survival in high-grade gliomas was assessed." (PMID 24937153, 2014). "Similarly, in gliomas with mutations in the TERT promoter, high levels of TERT mRNA were detected, possibly resulting from the specific mutations." (PMID 24937153, 2014).
glioma (continued). "Within Grade III-IV gliomas, those patients with the TERT promoter mutations alone had the poorest prognosis (median 11.5 months), while tumors bearing the events typically representative of astrocytomas (IDH1/2 mutation) had a more favorable prognosis (median 56.9 months)." (PMID 24722048, 2014). "Interestingly, previous studies have shown that C228T and C250T mutations in the TERT promoter may have different molecular mechanisms and varying impacts on the prognosis of glioma patients." (PMID 39804195, 2025). "Some molecular markers, such as IDH, 1p/19q codeletion, EGFR amplification, CDKN2A/B loss, and TERT promoter mutation, etc. have been routinely tested in clinical practice and cooperated with histopathological information to form the classification scheme of glioma." (PMID 39906742, 2024). "Thus, the result of high PD-L1 expression in TERT mutated gliomas may also be of high clinical importance for therapy of highly aggressive glioblastomas." (PMID 33963441, 2021). "Several previous studies have shown associations between TERT-p mutations and adverse clinicopathologic parameters or poor prognosis in various types of human cancers, including thyroid papillary carcinoma, melanoma, bladder cancer, and glioma, which was the main motivation for the present study." (PMID 33635430, 2021). "TERT promoter mutations may not serve as diagnostic markers on their own as there are other types of IDH-wildtype glial neoplasms that may harbor TERT promoter mutations, including pleomorphic xanthoastrocytoma, ganglioglioma, anaplastic glioma with piloid features, and ependymoma." (PMID 33228806, 2020). "Finally, TERT promoter mutations have a clear association with aggressive behavior in the setting of glioblastoma, and this is the most sensitive (66.7%) but least specific (89.4%) parameter, largely since TERT promoter mutations can be seen in other gliomas or systemic cancers." (PMID 30967140, 2019). "Hotspot mutations in the TERT promoter (C228T and C250T) are currently recognized as the only event in gliomas to upregulate TERT transcripts, and mRNA of TERT tends to be increased in TERT-mutated gliomas compared with normal brain tissue or TERT-wildtype gliomas." (PMID 29693015, 2018). "Mutations in the TERT promoter may also be useful for glioma diagnosis and prognosis." (PMID 28915660, 2017). "Our study indicates that TERT rs2853676 polymorphisms correlate with glioma survival and recurrence rates in a Chinese population, which suggests that they could potentially serve as prognostic markers in glioma patients." (PMID 27655710, 2016). "Several lines of research suggest that rs2853669 suppresses the TERT promoter mutation-mediated TERT expression regulation and mortality or recurrence rates for bladder cancer, gliomas, and renal cell cancer; however, the mechanism by which TERT transcription is regulated remains unknown." (PMID 26575952, 2016). "In conclusion, this meta-analysis suggests that the TERT genetic polymorphism rs2853676 is associated with an increased risk of glioma, lung adenocarcinoma and ovarian cancer among Caucasians, suggesting that the association may be cancer-type and ethnically specific." (PMID 26042809, 2015). "In contrast, the development of IDH-wildtype gliomas relies on the synergistic activation of multistep oncogenic pathways, such as EGFR amplification and TERT promoter mutation." (PMID 41602776, 2026).
glioma (continued). "In 38 patients with glioma, mutations in IDH1/2 (n = 4, 10.5%), TERT promoter (n = 15, 39.5%), 1p/19q codeletion (n = 1, 2.6%), and H3-3A (n = 1, 2.6%) were detected." (PMID 41163986, 2025). "In adult‐type gliomas with an IDH mutation, TERT promoter mutation correlates with a better prognosis; while this distinction is not evident in the context of GBM." (PMID 39804195, 2025). "For example, pediatric gliomas are enriched for MAPK pathway alterations and gene fusions, while adult gliomas more commonly harbor IDH mutations, TERT promoter mutations, and EGFR amplifications." (PMID 41284071, 2025). "Currently, common molecular markers associated with the prognosis of glioma include IDH, MGMT, telomerase reverse transcriptase (TERT), the short arm of chromosome 1 and the long arm of chromosome 19 (1p/19q)." (PMID 40860684, 2025). "At the same time as anatomical segmentation, the prediction of molecular biomarkers for gliomas—like IDH mutation, 1p/19q co-deletion, and TERT promoter mutation—has become increasingly important in the context of radiogenomics." (PMID 41007223, 2025). "Within that study, it was found that mutations in the TERT promoter occurred significantly more often in IDH1 wildtype glioblastomas (187 out of 322; 58%) compared to IDH1-mutated gliomas (10 out of 36; 28%; p = 0.0056)." (PMID 40564017, 2025). "Similar to adult‐type gliomas overall, we have observed that the influence of the TERT promoter on prognosis remains consistent across different EGFR statuses." (PMID 39804195, 2025). "Although telomerase reverse transcriptase (TERT) promoter mutation is a marker of aggressiveness in numerous cancers and central nervous system tumors, the role of TERT promoter alterations such as methylation has been debated in PitNETs." (PMID 40959438, 2025). "In Wang’s study, TPOT was used to identify IDH‐mutant TERT promoter‐mutant gliomas, reaching an AUC of 0.952 in the independent validation set." (PMID 38492096, 2024). "Despite the inclusion of more feature selection and classification algorithms, there is a paucity of clinical research on the TERT promoter subtypes of grade 1–4 gliomas." (PMID 39131044, 2024). "None of the CN patients examined in the present study presented any mutations in the TERT promoter or ATRX region, which are frequently observed in glioma." (PMID 38609519, 2024). "TERT promoter mutations are the most common (74%) in GBM patients, distinguishing GBM from low grade gliomas." (PMID 38615034, 2024). "To decrease the possibility that individuals with TERTwt glioma are wrongly predicted as TERTmut, we changed the cutoff value to reach a specificity of at least 90% for TERT mutant prediction." (PMID 38982347, 2024). "Oligodendrogliomas are defined as gliomas with IDH mutation and 1p/19q codeletion, and they also usually have a mutation in the TERT promoter." (PMID 39767683, 2024). "When compared with ANOVA and Relief, RFE also did not exhibit significant differences in its ability to differentiate TERT subtypes in glioma patients." (PMID 39131044, 2024). "Overall, approximately 80% of adult grade II/III gliomas and secondary glioblastoma multiforme (GBM) harbor mutations at either Arg132 of IDH1 or Arg172 of IDH2, whereas point mutations in the TERT promoter occurred in ~75% of GBM." (PMID 38232086, 2024).